UBE2V2 (ubiquitin conjugating enzyme E2 V2)
Description:
Has no ubiquitin ligase activity on its own. The UBE2V2/UBE2N heterodimer catalyzes the synthesis of non-canonical poly-ubiquitin chains that are linked through 'Lys-63'. This type of poly-ubiquitination does not lead to protein degradation by the proteasome. Mediates transcriptional activation of target genes. Plays a role in the control of progress through the cell cycle and differentiation. Plays a role in the error-free DNA repair pathway and contributes to the survival of cells after DNA damage.
Synonyms: EDAF-1; EDPF-1; MMS2; UEV2; UEV-2; DDVit-1; EDPF1; DDVIT1
Tractability: Small molecule: a structure with a bound ligand is known. PROTAC: ubiquitination databases record sites on it; its protein half-life has been measured.
Gene: Protein-coding gene on chromosome 8 (48,008,410 to 48,064,708, forward strand). Ensembl gene ENSG00000169139.
Subcellular location (Human Protein Atlas): Nucleoplasm
Pathways (Reactome):
DNA Repair: Formation of Incision Complex in GG-NER; Nonhomologous End-Joining (NHEJ); Processing of DNA double-strand break ends; Recruitment and ATM-mediated phosphorylation of repair and signaling proteins at DNA double strand breaks
Cell Cycle: G2/M DNA damage checkpoint
Immune System: Antigen processing: Ubiquitination & Proteasome degradation
Metabolism of proteins: E3 ubiquitin ligases ubiquitinate target proteins
Gene Ontology:
Molecular function: protein binding
Biological process: DNA double-strand break processing; positive regulation of double-strand break repair; positive regulation of protein K63-linked ubiquitination; protein K63-linked ubiquitination; protein polyubiquitination; protein ubiquitination; regulation of DNA repair
Cellular component: extracellular exosome; nucleoplasm; nucleus; UBC13-MMS2 complex; cytoplasm
Genetic constraint (gnomAD): Loss-of-function variants: 6 observed, 9.9 expected, observed/expected ratio (o/e) 0.61, 90% interval 0.33 to 1.2. That is too few expected variants to judge how well the gene tolerates losing a copy. Missense variants: 125 observed, 141.45 expected, observed/expected ratio (o/e) 0.88, 90% interval 0.76 to 1.02. Synonymous variants: 59 observed, 46.2 expected, observed/expected ratio (o/e) 1.28, 90% interval 1.03 to 1.59.
Homologues: Orthologues: macaque UBE2V2 (100% identical), mouse Ube2v2 (99% identical), pig UBE2V2 (96% identical), zebrafish ube2v2 (94% identical), Drosophila melanogaster Uev1A (66% identical), Caenorhabditis elegans uev-1 (61% identical). Paralogues in human: UBE2V1 (88% identical), UBE2T (30% identical), UBE2K (28% identical), UBE2A (28% identical), CDC34 (27% identical), UBE2B (27% identical), UBE2N (27% identical), UBE2O (27% identical), UBE2J1 (26% identical), UBE2C (25% identical), UBE2R2 (25% identical), AKTIP (24% identical), and 12 more.
Diseases named in the same sentence as UBE2V2 in open-access papers:
UBE2V2 is named in the same sentence as 22 diseases in open-access papers, as found by Europe PMC text mining. Sharing a sentence is not in itself a finding about the gene and the disease. The quoted sentences say what the papers report.
breast carcinoma (8 papers, 2011 to 2022). "Studies that report the role of UBE2V2 in cancer are comparatively few, the gene is reported to be associated with poor prognosis in breast cancer while the suppression of the gene in colorectal carcinoma cells is known to reverse oxaliplatin resistance." (PMID 26808319, 2016). "Differential expression of UBE2V2 has also been associated with poor prognosis in breast cancer." (PMID 31835700, 2019). "UBE2V2 contributes to the development and progression of many cancers, including prostate, oropharyngeal, and breast cancers, via promoting cell proliferation, suppressing cell apoptosis, and regulating immune signaling." (PMID 34555052, 2021). "In total, 11 DNA repair genes (UBE2A, RBBP8,RAD50, FAAP20, RPA3, ENDOV, DDB2, UBE2V2,MRE11, RRM2B, andPARP3) were preserved as prognostic genes to estimate risk score, which was applied to establish the prognostic model and stratified breast cancer patients into two groups with high or low risk." (PMID 36713553, 2022). "The hazard ratio of five genes (RBBP8,PARP3, ENDOV, UBE2V2, and DDB2) was <1, which plays a protective role in developing breast cancer." (PMID 36713553, 2022). "A total of 11 DNA repair genes, namely, UBE2A, RBBP8,RAD50, FAAP20, RPA3, ENDOV, DDB2, UBE2V2,MRE11, RRM2B, andPARP3, were involved in the prognostic model for breast cancer patients." (PMID 36713553, 2022). "In progesterone receptor-negative breast cancer patients, the expression level of UBE2V2 and UBE2A was higher than in patients with progesterone receptor-positive breast cancer." (PMID 36713553, 2022).
prostate carcinoma (6 papers, 2019 to 2025). A carcinoma that arises from epithelial cells of the prostate gland. "In familial prostate cancer, however, a high frequency variant of UBE2V2 was identified and found to affect DNA repair and androgen signaling." (PMID 31835700, 2019). "In prostate cancer, its overexpression inhibits proliferation and induces apoptosis by targeting UBE2V2, demonstrating tumor-suppressive properties." (PMID 40004152, 2025). "When compared with the normal tissues, the protein expression levels of UBE2V2 in prostate cancer tissues were significantly upregulated." (PMID 34429120, 2021). "In this study, we measured the expression of Ubiquitin Conjugating Enzyme E2 V2 (UBE2V2) in prostate cancer tissues and cell lines by WB and explored the effect of UBE2V2 on the proliferation characteristics of prostate cancer by MTT and colony formation test." (PMID 34429120, 2021). "The cell proliferation caused by miR-499a can inhibit the proliferation and migration of prostate cancer cells by inhibiting the expression of UBE2V2 in prostate cancer cells." (PMID 34429120, 2021). "At the same time, we found that miR-499a combined with UBE2V2 inhibited the expression of UBE2V2 in prostate cancer cells." (PMID 34429120, 2021). "All in all, these studies suggested that miR-499a negatively regulated UBE2V2 expression by directly binding to the 3′-UTR region of UBE2V2 in prostate cancer." (PMID 34429120, 2021). "In order to investigate the role of UBE2V2 on prostate cancer, 3 pairs of prostate cancer tissues and peritumoral tissues (normal) were used to measure the expression levels of UBE2V2." (PMID 34429120, 2021). "In conclusion, our results indicate that miR-499a inhibits the proliferation of human prostate cancer cells by targeting UBE2V2, which will provide a potential target for the treatment of prostate cancer." (PMID 34429120, 2021). "Professor Alanne identified PIAS3 as a potential biomarker for Gleason score 4 + 3 = 7 for prostate cancer and UBE2V2 as a potential biomarker for Gleason score 6, while Professor ElKarami created a model for predicting upgrading on magnetic resonance imaging targeted biopsy by machine learning." (PMID 35978830, 2022). "In our research, we found that the UBE2V2 protein level in prostate cancer cell lines was significantly higher than the UBE2V2 protein level in normal prostate cells, and the mRNA expression level did not change significantly compared with normal prostate tissue cells." (PMID 34429120, 2021). "Based on our research, we believe that the abnormal expression of miR-499a and UBE2V2 in tissues and samples may be closely related factors affecting the occurrence and development of prostate cancer." (PMID 34429120, 2021). "Therefore, we tried to explore the role of miR-499a-UBE2V2 pathway in prostate cancer." (PMID 34429120, 2021).
glioma (2 papers, 2021 to 2024). A benign or malignant brain and spinal cord tumor that arises from glial cells (astrocytes, oligodendrocytes, ependymal cells). "Additionally, ATIP1 expression, as well as that of the ATIP1 upstream (SHP-1) and downstream regulator (MMS2/UBE2V2) proteins, correlated with glioma progression." (PMID 33809019, 2021).
lung adenocarcinoma (2 papers, 2021 to 2023). A carcinoma that arises from the lung and is characterized by the presence of malignant glandular epithelial cells. "Moreover, UBE2V2 is an independent prognostic indicator for lung adenocarcinoma, which is closely related to the mutational processes of cigarette smoking." (PMID 34555052, 2021). "In lung adenocarcinoma, overexpression of UBE2V2 is positively correlated with PD‐L1 mRNA level, T classification, and poor survival rate in LUAD patients based on TCGA and IHC." (PMID 37755128, 2023). "The expression of UBE2V2 in four kinds of lung adenocarcinoma cells was higher than that in normal bronchial epithelial cells." (PMID 37755128, 2023). "However, the relationship between UBE2V2 expression and the morbidity of lung adenocarcinoma (LUAD) is still unknown." (PMID 37755128, 2023). "The results showed that high expression of UBE2V2 (GSE31210 p = 0.003 and GSE13213 p < 0.001) predicted poorer survival in lung adenocarcinoma patients." (PMID 37755128, 2023).
gastric cancer (1 paper, 2012). A primary or metastatic malignant neoplasm involving the stomach. "In addition, it was the first time for this findings that expression of MCM4PRKDC, and UBE2V2 at 8q11.21, or YWHAZANKRD46ZNF706, and GRHL2 at 8q22.3 was co-regulation and was concordantly up-regulated in the samples of gastric cancer with amplification at 8q11.21 or 8q22.3." (PMID 22559327, 2012).
lung carcinoma (1 paper, 2023). "UBE2V2 may be a valuable therapeutic target for lung cancer." (PMID 37755128, 2023).
lymph node metastasis (1 paper, 2023). "IHC showed that UBE2V2 was related to the following clinicopathological factors: gender (p = 0.043), stage (p = 0.042), and lymph node metastasis (p = 0.002)." (PMID 37755128, 2023). "The results of IHC analysis suggested that UBE2V2 was related to lymph node metastasis." (PMID 37755128, 2023).
melanoma (1 paper, 2023). A malignant, usually aggressive tumor composed of atypical, neoplastic melanocytes. "UBE2V2 was highly expressed in malignant melanoma, and knocking down it reduced melanoma cell proliferation and subcutaneous tumor growth." (PMID 37755128, 2023). "Inhibiting the expression of UBE2V2 upregulated the expression of E‐cadherin (an EMT marker) only in melanoma." (PMID 37755128, 2023).
pneumonia (1 paper, 2018). An acute, acute and chronic, or chronic inflammation focally or diffusely affecting the lung parenchyma, caused by an infection in one or both of the lungs (by bacteria, viruses, fungi, or mycoplasma.). "Thus, the downregulated UBE2V2 will result in abnormal differentiation of monocytes and more proinflammatory will be produced, which in turn aggravates pneumonia." (PMID 30405317, 2018). "Simultaneously, based on target gene prediction and qRT-PCR analysis, we found that genes MYCBP2, UBE2V2, and UBE2D2 may play important roles in viral replication and Adv-induced pneumonia." (PMID 30405317, 2018).
Stroke (1 paper, 2023). Sudden impairment of blood flow to a part of the brain due to occlusion or rupture of an artery to the brain. "An experimental stroke model and human neutrophil-like HL-60 cells were further transfected with agomiR-193a-5p/antagomiR-193a-5p or ubiquitin-conjugating enzyme V2 (UBE2V2)-siRNA prior to model induction for in vivo and in vitro studies." (PMID 35906328, 2023).
cancer (11 papers, 2011 to 2025). A tumor composed of atypical neoplastic, often pleomorphic cells that invade other tissues. "For example, UBE2V2 is a variant ubiquitin-conjugating E2 enzyme that is orthologous to the yeast MMS2 gene, implicated in HR and translesion synthesis, that has been shown to promote UV resistance in human cells, with overexpression linked to poor prognosis in some cancer types." (PMID 27863405, 2017). "As a member of the ubiquitin‐conjugating enzyme (E2) family, UBE2V2 demonstrates significant tumorigenicity in many cancers." (PMID 37755128, 2023). "The special structural features of UBE2V2 may result in different functions in cancer from other classic E2 enzymes." (PMID 37755128, 2023). "Intriguingly, there were no striking differences between cancer and adjacent tissues in UBE2V2 mRNA levels." (PMID 34429120, 2021).
tumor (5 papers, 2017 to 2025). "Collectively, the results of IHC showed that UBE2V2 was correlated with three factors: Gender (p = 0.043), tumor stage (p = 0.042), and lymph node metastasis (p = 0.002) in LUAD." (PMID 37755128, 2023). "The results show that KRT8, PSMD2, TRIM28, and UBE2V2 are significantly overexpressed in tumor tissues, while the expression level of FBXO9, MYLIP, and RNF180 is significantly reduced in LUAD (p < 0.05)." (PMID 35711913, 2022).
infection (2 papers, 2021 to 2023). The state of being infected such as from the introduction of a foreign agent such as serum, vaccine, antigenic substance or organism. "The results of WB showed that the expression of UBE2V2 was significantly downregulated by UBE2V2‐shRNAs lentiviruses infection compared to shRNA‐Con lentiviruses infection." (PMID 37755128, 2023).
UBE2V2 also shares sentences with these, for which no sentence is quoted: colon cancer (2 papers); viral infection (2); adrenocortical carcinoma (1); colorectal carcinoma (1); familial prostate cancer (1); ovarian serous cystadenocarcinoma (1); rectal adenocarcinoma (1); sarcoma (1); uterine carcinosarcoma (1).